TLR4 (toll like receptor 4)
Diseases named in the same sentence as TLR4 in open-access papers (continued):
Sharing a sentence is not in itself a finding about the gene and the disease.
eosinophilia (16 papers, 2011 to 2023). "Astragalin ameliorated oxidative stress-associated epithelial eosinophilia and apoptosis through disturbing TLR4-PKCβ2-NADPH oxidase-responsive signaling." (PMID 25069610, 2014). "In contrast to the clear impact of defective MHCII or TSLPR expression on airway eosinophilia, we found that responses in TLR4-KO mice were, for the most part, similar to the responses in wild-type C57BL/6 mice." (PMID 31164097, 2019). "If augmented by TLR-4 driven eosinophilia as observed in AMP-LPS treated mice, these findings suggest AMP-LPS as a stronger stimulus for allergic inflammation in the airways over LPS alone." (PMID 29357863, 2018). "Urban PM2.5 containing trace microbial elements may exacerbate allergic inflammation and eosinophilia in the murine lung via a TLR2/TLR4/MyD88-signaling pathway." (PMID 33809902, 2021). "After demonstrating the relationship between SIgA levels and eosinophils controlling larval migration, and after verifying the increase in the expression of TLR2 and TLR4 in single-infected mice, we assessed the potential role of TLRs in triggering SIgA production and eosinophilia." (PMID 34784389, 2021). "With cell transfers of TLR4-deficient MCs, mice developed Th2 responses and eosinophilia while with TLR4-deficient MCs they failed to develop it." (PMID 29867994, 2018). "We also assessed the affects of TLR2, TLR4 and MyD88 on eosinophilia in the blood in AAD." (PMID 27309732, 2016). "In KSpn-mediated suppression of AAD we identified important suppressive roles for: TLR2 in eosinophil infiltration into the airways (partial) and AHR; TLR4 in eosinophilia of the airways and blood, IL-5 and IL-13 release from splenocytes and AHR, and; MyD88 in airway and blood eosinophilia and AHR." (PMID 27309732, 2016). "TLR4-deficient mice challenged with either OVA preparation showed eosinophilia but not neutrophilia and had increased IL-5." (PMID 24968337, 2014). "However, PM2.5-bound LPS may be a strong candidate for exacerbation of lung eosinophilia caused by PM2.5, indicated by the strong inhibition of effects in TLR4−/− mice." (PMID 28887522, 2017). "Furthermore, this study elucidated whether astragalin encumbered airway eosinophilia and epithelial apoptosis through disturbing TLR4-NADPH oxidase pathway responsive to LPS." (PMID 25069610, 2014). "Specifically, the exacerbative effects of LPS and H-ASD on OVA-induced lung eosinophilia were investigated using wild-type (WT), TLR2−/−, TLR4−/− and MyD88−/− mice with BALB/c background." (PMID 31889961, 2019). "The results of our study indicate that the murine lung eosinophilia exacerbated by co-exposure of LPS and H-ASD is not only mediated by TLR4/MyD88 signaling pathway, but also TLR4-independent signaling pathways." (PMID 31889961, 2019). "Thereby the combination of elevated non-TLR4 driven TNF-α and TLR-4 driven eosinophilia observed in AMP-LPS treated mice suggest AMP-LPS is a stronger stimulus for allergic inflammation in the airways than LPS alone." (PMID 29357863, 2018). "The increased expression of TLR2 and TLR4 to the antigen surface of O. occidentalis may contribute to the initiation of immune responses, including Th2-cell responses that generally result in eosinophilia, goblet and mucosal mast-cell hyperplasia, which lead to the elimination of the parasite." (PMID 26622306, 2015). "Addition of eLPS during Bt sensitization resulted in inhibition of airway eosinophilia in WT and also in CD14−/−, TLR4−/− and TLR2−/− mice, suggesting that these molecules are dispensable for the inhibition of airway eosinophilia induced by eLPS." (PMID 23805294, 2013). "Secondly, the lung eosinophilia was more severe in TLR2−/− mice than in TLR4−/− mice, probably due to the fact that TLR2 is not involved in the immune response to LPS." (PMID 31889961, 2019).
eosinophilia (continued). "Then in AAD we identified inductive roles for: TLR2 in IL-5 release from MLN T cells, IL-5 and IL-13 release from splenocytes and AHR; TLR4 in eosinophil infiltration into BALF and blood (partial) and AHR, and; MyD88 in blood eosinophilia, IL-13 release from MLN T cells and AHR." (PMID 27309732, 2016). "We found that eLPS did not suppress airway eosinophilia in MyD88- or IFN-γ ̃deficient mice while suppression was observed in mice deficient in CD14, TLR4 or TLR2 molecules." (PMID 23805294, 2013). "HDM induced DC activation through TLR4, activating Th2 response in an adjuvant-free murine model; the use of TLR4 antagonist (underacyletd form of R. spharoides LPS) reduced airway inflammation to the baseline level of non-sensitized mice, in terms of eosinophilia and lymphocytosis." (PMID 37426425, 2023). "Here, we found that inhalation of FAP by naïve mice led to airway eosinophilia that was dependent on protease-activated receptor-2 (PAR2), but not TLR2 and TLR4." (PMID 30575775, 2018). "Augmented TLR4 driven eosinophilia and greater TNF-α responses observed in AMP-LPS treated mice independent of TLR-4 expression, suggests activation of allergic responses by TLR4 and non-TLR4 pathways larger than those induced by LPS administered alone." (PMID 29357863, 2018). "Moreover, it appears that TLR-4 and IFN-γ were not directly involved in the A. baumannii-induced suppression of airway eosinophilia." (PMID 21789200, 2011).
hepatitis B (16 papers, 2014 to 2025). "Precedent exists for utilizing a TLR4 agonist in humans: the licensed vaccines Fendrix, for the prevention of hepatitis B, and Cervarix, the HPV vaccine, both utilize the TLR4 agonist monophosphoryl lipid A." (PMID 31145733, 2019). "Monophosphoryl Lipid A (MPL), a potent agonist of TLR4, is currently in use in combination with alum in vaccines against hepatitis B and papilloma virus in adults." (PMID 29541075, 2018). "Monophosphoryl lipid A (MPLA) is a Toll-like receptor 4 (TLR4) agonist with more than 100,000 human doses safely administered as a part of licensed hepatitis B and Human papillomavirus vaccines." (PMID 25144181, 2014). "Another adjuvant, AS04, a combination of alum and a toll-like receptor 4 (TLR4) agonist, is used in HPV and hepatitis B vaccines to enhance the immune response." (PMID 40333258, 2025). "MPLA is a TLR4 agonist (extracted from Salmonella Minnesota), binds to TLR4-MD2, and has been used as a vaccine adjuvant against cervical cancer and hepatitis B." (PMID 32023919, 2020). "The most developed TLR4-stimulating adjuvant is monophosphoryl lipid (MPL), the first to obtain approval for use in human vaccines against viral pathogens such as herpes zoster, Hepatitis B, and human papillomavirus (HPV)." (PMID 36291919, 2022). "Monophosphoryl lipid A, a chemically modified product of LPS, was the first TLR4 agonist approved for use in human vaccines, and it is currently included in CervarixTM, a vaccine for human papillomavirus (HPV) and FENDrixTM, a vaccine for hepatitis B." (PMID 29636723, 2018). "In a hepatitis B virus infection model, TLR4-intact young mice failed to resolve viruses and developed chronic infections, while their TLR4 mutant counterparts exhibited rapid viral clearance, suggesting that an immune-tolerant pathway mediated by TLR4 signaling was predominant in young mice." (PMID 31333675, 2019).
Hypercholesterolemia (16 papers, 2011 to 2025). An increased concentration of cholesterol in the blood. "Therefore, IH could cause glycolipid metabolism disorders and TLR4 was involved in IH-mediated hypercholesterolemia." (PMID 29673358, 2018). "The present work elucidates a mechanism by which bone‐derived SAA3 inhibits the expression of CYP7A1 by binding to TLR4 on hepatocytes and thereby phosphorylates c‐Jun, which leads to hypercholesterolaemia in Tsc1Dmp1 mice." (PMID 38613835, 2024). "The aorta exhibited intimal hyperplasia, foam cells, and elevated expression mRNA of TLR-2 and TLR-4 in diet-induced hypercholesterolemia." (PMID 24901254, 2014). "When being exposed to HFD, the toll-like receptor 4 (TLR4) of HSPCs can be activated by sensing endogenous ligands such as damaging associated molecular patterns (DAMPs), which are released during inflammation caused by hypercholesterolemia." (PMID 40519937, 2025). "Moreover, a high-cholesterol diet leads to excessive hypercholesterolemia during pregnancy in rats, which enhances TLR4 activity in uterine arteries, resulting in uterine artery dysfunction and perinatal complications." (PMID 40218311, 2025). "The involvement of TLR4‐c‐Jun in Tsc1Dmp1‐induced hypercholesterolaemia was next examined." (PMID 38613835, 2024). "Additionally, hypercholesterolemia promotes germinal centre formation and the generation of autoantibodies against ds‐DNA and nucleosome in a TLR4/ IL27‐dependent mechanism." (PMID 36098213, 2022). "Therefore, the TLR-2 expression observed in this study may be related to TLR-4 upregulation and/or hypercholesterolemia." (PMID 24901254, 2014). "CH reduces hypercholesterolemia-mediated atherosclerosis via modulating the inflammatory genes expression including TNF-α, toll-like receptors (TLR4), IL-17, and NLRP3 in the intestine and aorta compared with hypercholesterolemia control rats." (PMID 38966181, 2024). "The addition of systemic inflammation to hypercholesterolemia significantly increased mRNA expression of TLR-2 and TLR-4 and exacerbated atherosclerotic lesions within the aorta." (PMID 24901254, 2014). "Endothelial cell-specific TLR-2 expression is also upregulated via shear stress and hypercholesterolemia independent of TLR-4 expression." (PMID 24901254, 2014).
keratitis (16 papers, 2010 to 2026). A corneal disease that is characterized by inflammation of the cornea. "The altered activation of TLR4-related pathway in KC-HCFs may underlie the pathogenesis of potential secondary keratitis following crosslinking." (PMID 39869570, 2025). "In summary, we proved that thymol played a protective part in A. fumigatus keratitis by cutting down inflammatory cells aggregation, downregulating the TLR4/ MyD88/ NF-kB/ IL-1β signal expression and reducing necroptosis and pyroptosis." (PMID 36517045, 2023). "Previously, we have shown that TLR4 deficient BALB/c mice showed increased corneal opacity, and corneal perforation which manifests itself by increasing susceptibility to keratitis, as compared to WT control mice." (PMID 36422579, 2022). "The host-cytokine response towards P. aeruginosa keratitis is mainly induced by LPS stimulation of TLR4/MD-2 and flagellin binding to TLR5." (PMID 33208864, 2020). "Our results clearly indicate that ATF4 was involved in the host antifungal immune response to A. fumigatus keratitis; expression was found to be dependent on TLR4, LOX-1 expression, and MAPKs pathway." (PMID 30647960, 2018). "We were able to confirm that ATF4 was involved in host antifungal immune response in A. fumigatus keratitis and was dependent on TLR4, LOX-1 expression, and MAPKs pathway." (PMID 30647960, 2018). "Although the discrepancy between these studies is yet to be resolved, the results of the present study clearly indicated that activation of TLR4 on corneal epithelial cells in vitro and in vivo stimulate cytokine production and development of keratitis." (PMID 24633052, 2014). "Likewise, another study showed that glycyrrhizin reduced HMGB1, TLR4, IL‐1β and IL‐12 and was protective against keratitis." (PMID 34953035, 2022). "The dominant inducer appears to be the flagellin, and this conclusion is supported by studies of murine keratitis provoked by P. aeruginosa infection, wherein LPS stimulation of TLR4 occurred only in animals infected with a flagellin-mutant strain of P. aeruginosa." (PMID 28469996, 2017). "Stromal infiltration of CD68+ve positive cells was seen in both herpetic and gram-negative keratitis sections, associated with TLR3 and TLR4 expression in the corneal epithelium, respectively." (PMID 24736562, 2014).
leprosy (16 papers, 2012 to 2025). Leprosy is a chronic infectious disease affecting primarily the skin and peripheral nervous system. "In leprosy, TLR4 activation can be deleterious to the host as it contributes to the damaging inflammation responsible for leprosy lesions, with genetic association studies having shown that TLR4 polymorphisms are protective against leprosy." (PMID 36993966, 2023). "TLR1G>T (rs5743618), TLR2T>C (rs1816702), TLR2 T>C (rs4696483), and TLR4 A>G (rs1927911) genotype and allele frequency distributions between leprosy patients and control group." (PMID 36313452, 2022). "Based on the participation of Toll receptors in modulating the immune response to infection by M. leprae, we suggested that genetic variations in the TLR1, TLR2, and TLR4 genes are somehow associated with leprosy." (PMID 36313452, 2022). "A genetic association study using a cohort of 441 Ethiopian leprosy patients and 197 healthy controls reported that two single nucleotide polymorphisms of TLR4 (896G → A and 1196C → T) were associated with protection against leprosy." (PMID 27458573, 2016). "Moreover, the use of molecular methods applied to identify single nucleotide polymorphism (SNP) of Toll-like receptors (TLRs), particularly TLR1, TLR2 and TLR4, have been reported to be associated with distinct leprosy clinical manifestations (19–23." (PMID 37187734, 2023). "However, the issue of TLR4 polymorphisms and disease risk still remains controversial; another study revealed that the mutation of TLR4 is positively associated with the risk of developing leprosy." (PMID 27652268, 2016). "Other mycobacterial species possess ligands for TLR4 and genetic association studies in human populations suggest that people with TLR4 polymorphisms may be protected against leprosy." (PMID 27458573, 2016). "In addition, genetic polymorphisms in TLR1, TLR2, and TLR4 are associated with leprosy and/or leprosy reactions." (PMID 23350010, 2013). "PB-type leprosy more commonly exhibits TLR1 and TLR2, while MB-type leprosy more commonly exhibits TLR4." (PMID 41239264, 2025). "In leprosy, the infection of macrophages results in the recognition by TLR-4 and TLR-2/1, and subsequent direction of adaptive immune responses." (PMID 38116294, 2023). "Two miRNAs that target PRKCE gene (hsa-miR-1-3p and hsa-miR-31-5p), which in turn is involved in TLR-4 signaling in mycobacterial infections, showed low expression in leprosy tissues of both TT and LL poles through miRNA sequencing." (PMID 38116294, 2023). "The aim of the present study was to investigate the association between the single nucleotide polymorphism (SNP) rs1927914 A/G in TLR4 gene and the immunological profile of household contacts (HHC) of leprosy patients." (PMID 37187734, 2023). "It has been shown that while TLR2 SNP was associated with increased risk for leprosy, TLR1 and TLR4 SNP were associated with differential production with chemokine and cytokines." (PMID 37187734, 2023). "The present study intended to investigate the association between TLR4 SNP and the immunological profile of household contacts (HHC) of leprosy patients." (PMID 37187734, 2023). "In some cases, such as TLR2 in the context of TB and leprosy and TLR4 in the context of TB, this abrogated function correlates unsurprisingly with increased susceptibility of the host to infection." (PMID 22529866, 2012). "The main goal of the present investigation was to evaluate the interplay between the operational classification [HHC(PB) and HHC(MB)] and the SNP TLR4 rs1927914 in household contacts living in Governador Valadares, Minas Gerais State, Brazil, a hyperendemic area for leprosy." (PMID 37187734, 2023). "Signaling through TLR4 could shift the immunological balance from localized to disseminated disease in leprosy." (PMID 27458573, 2016).
leprosy (continued). "The general trend of up-regulation of TLR4 expression in macrophages derived from the unvaccinated donors after incubation with low MOI of M. leprae provides further support of an important role of TLR4 in leprosy." (PMID 27458573, 2016). "This indicates a possible role of TLR4 in leprosy and leprosy reactions." (PMID 27458573, 2016). "TLR4 1196 C>T effects were similar to TLR4 896 A>G for brucellosis, cutaneous leishmaniasis, leprosy, typhoid fever and S. pyogenes tonsillar disease, and was protective for bacterial vaginosis in pregnancy (0.55; 95%CI 0.31-0.98) and Haemophilus influenzae tonsillar disease (0.42; 95%CI 0.17-1.00)." (PMID 24282567, 2013). "Interestingly, not all outcomes were negative and the TLR4 896 A>G polymorphism was associated with significant protection against leprosy (ORG 0.36; 95% CI 0.22-0.60) in East Africa." (PMID 24282567, 2013). "When comparing leprosy patients to HHC, 16 genes showed significantly different expression for leprosy patients (increased: FCGR1A, IL6, IL15, LRKK2, MBP, MSR1, PACRGv1, TLR1, TLR4; decreased: CAMTA, CD3E, CTLA4, CXCL13, GATA3, LAG3, TFGB)." (PMID 31784594, 2019). "Currently there are four licensed vaccines that contain multiple TLR agonists, BCG that contains TLR2 and TLR4 agonists, Cervarix and Fendrix that contain alum and MPL, and Cadi-05 (Immuvac) (Mycobacterium indicus pranii) against leprosy." (PMID 26344621, 2014). "Toll-like receptors (TLR) 1, TLR2, TLR4, dendritic cell-specific intercellular adhesion molecule-3-grabbing non-integrin (DC-SIGN), and CD163 mediate the interaction between macrophages and M. leprae in leprosy, which increases IL-6 and IL-10 secretion." (PMID 41239264, 2025). "Additionally, we observed that a classification of leprosy patients is possible using transcriptomics since a set of genes were increased in BL/LL patients (CD46, CXCL10, FCGR1A, HDAC2 and TLR4) and TT/BT showed a higher expression of IL2 and TLR6." (PMID 31784594, 2019). "Conversely, another investigation found TLR4 D299G in a Malawi cohort of leprosy patients afforded no protection, although their cohort was half the size of the previous study." (PMID 22529866, 2012). "If this is the case, then our study may have implications in the treatment of leprosy and other mycobacterial diseases since the induction of IFN-β responses in lepromatous leprosy may be blocked by a treatment strategy that directly inhibits TLR4-TRIF signaling." (PMID 27458573, 2016).